LINC02563 (long independently transcribed non-coding RNA 2563)
Synonyms: CRAT40
Gene: Long non-coding RNA gene on chromosome 17 (65,457,541 to 65,458,408, forward strand). Ensembl gene ENSG00000263520.
Diseases named in the same sentence as LINC02563 in open-access papers:
LINC02563 is named in the same sentence as 3 diseases in open-access papers, as found by Europe PMC text mining. Sharing a sentence is not in itself a finding about the gene and the disease. The quoted sentences say what the papers report.
tumor (1 paper, 2025). "Consistent with the RNA-Seq results, LINC02563, also referred to as lnc-CRAT40 (accession number: NR_131984.1), a 277 bp transcript located on chromosome 17q24.1, was significantly elevated in tumor tissues compared with adjacent normal tissues." (PMID 40860198, 2025).
LINC02563 also shares sentences with these, for which no sentence is quoted: colorectal cancer (1 paper); lymph node metastasis (1).